MPO (myeloperoxidase)
Diseases named in the same sentence as MPO in open-access papers (continued):
Sharing a sentence is not in itself a finding about the gene and the disease.
brain injury (6 papers, 2014 to 2022). Acute and chronic (see also brain INJURIES, CHRONIC) injuries to the brain, including the cerebral hemispheres, CEREBELLUM, and brain STEM. "MPO is a key enzyme expressed in blood-borne neutrophils, macrophages and monocytes, and has been used as a marker for inflammation after brain injuries." (PMID 33445746, 2021). "Brain injury induced a significant increase in MPO levels in TBI group (1.5 folds, p < 0.0001)." (PMID 35322143, 2022). "Treatment with IAIPs reduced myeloperoxidase (MPO) staining and co-localization of MPO and matrix metalloproteinase 9 (MMP9) in the brain of neonatal rats exposed to HI-related brain injury." (PMID 33276548, 2020). "A recent study in a repetitive mild non-invasive traumatic brain injury mouse model showed that saffron extract and crocin suppress TBI-induced inflammatory and oxidative responses by decreasing the levels of IFN-γ, TNF-α, MPO, GSH, and MDA." (PMID 36232902, 2022).
diabetic kidney disease (6 papers, 2020 to 2025). Progressive kidney disorder caused by vascular damage to the glomerular capillaries, in patients with diabetes mellitus. "Oxidative stress induction and elevated MPO activity lead to the development of diabetic nephropathy." (PMID 39877627, 2025). "Increased MPO activity contributes to cardiovascular complications and diabetic nephropathy through NF-kβ pathway activation and chlorotyrosine formation." (PMID 39877627, 2025). "Clinical research has demonstrated that alprostadil can reduce the expression of inflammatory factors such as myeloperoxidase (MPO), TNF-α, and IL-6 in the treatment of ischemia reperfusion injury, contrast nephropathy, and diabetic nephropathy etc.." (PMID 31312872, 2020). "A pathologic relevance of these findings to human diabetic kidney disease is supported by congruent observations made upon immunostaining of H3Cit and MPO in human glomeruli of patients with DKD compared to non-DKD diabetic patients and non-diabetic patients." (PMID 35889923, 2022).
E. coli infection (6 papers, 2011 to 2022). "Three studies found gut inflammation (measured by calprotectin (CAL) and MPO) was positively associated with enterotoxigenic E. coli (ETEC) infection." (PMID 34778344, 2021). "Myeloperoxidase analysis also showed significantly less activity in lung homogenates of RAGE KO compared to wild type lungs after E. coli infection, consistent with the lower levels of neutrophils observed in the RAGE-deficient mice." (PMID 21629785, 2011). "Similarly, in vivo, CsA-treatment of mice decreased the renal resistance to uropathogenic Escherichia coli infection associated with decreased expression of neutrophil-attracting chemokines CXCL2 and CXCL1, and myeloperoxidase (MPO) in mouse kidneys." (PMID 34795676, 2021). "The levels of the inflammatory factors IL-2, IL-6, TNF-α, and MPO were significantly increased after E. coli infection, while MPX reduced the serum levels of IL-6 (p < 0.01), IL-2, TNF-α, and MPO (p < 0.05)." (PMID 34177825, 2021).
glomerulosclerosis (6 papers, 2017 to 2024). A hardening of the kidney glomerulus caused by scarring of the blood vessels. "The inverse association of leukocyturia and the fraction of glomerular sclerosis was maintained in both, PR3-ANCA GN (p = 0.034, r = − 0.465) and MPO-ANCA GN (p = 0.044, r = − 0.443)." (PMID 36542276, 2023). "This study indicated that oleuropein decreases elevated serum NO and kidney and liver MPO activity, and has beneficial effects on kidney function test, leukocyte infiltration, glomerular hypertrophy and glomerulosclerosis in diabetic rats." (PMID 28975102, 2017). "Since the protective effects of oleuropein on glomerulosclerosis, MPO activity, NO, and kidney function test in diabetic rats have not previously been done." (PMID 28975102, 2017). "This study showed that oleuropein has beneficial effects in decreasing the elevated serum NO, MPO, urea, and creatinine, and protective effects on leukocyte infiltration and glomerulosclerosis in diabetic rats." (PMID 28975102, 2017). "The objectives of the present study were to investigate the protective effects of oleuropein on glomerulosclerosis, MPO activity, NO, and kidney function test in diabetic rats." (PMID 28975102, 2017). "Histological differences between MPO-AAV and PR3-AAV have been found in several reports: namely, more fibrotic changes, such as glomerulosclerosis, interstitial fibrosis, and tubular atrophy, are typically recognized in MPO-AAV than in PR3-AAV." (PMID 36926340, 2023). "Moreover, patients with MPO-ANCA and MPA have a more pronounced chronic injury manifesting as glomerulosclerosis, interstitial fibrosis, and tubular atrophy when compared to those with PR3-ANCA and GPA." (PMID 33916214, 2021).
hematoma (6 papers, 2018 to 2024). A hematoma is a collection of blood from a vascular structure into an extravascular space. "The results revealed a significant increase in MPO and IL-1β positive cells around the hematoma after ICH, indicating a severe inflammatory reaction." (PMID 38658922, 2024). "Immunostaining (× 200 and × 400) results showed that NLRC4 siRNA treatment reduced MPO-positive cells around the hematoma compared to the ICH group." (PMID 34848837, 2021). "Compared with the Sham-group, both Simva-group and Veh-group showed a lot of MPO (+) cells in the area around the hematoma, in which the MPO (+) cells count in the Simva-group was less than the control one on the days 1, 3, and 7 post-ICH." (PMID 30631264, 2018). "Moreover, fewer MPO-positive cells were found around the hematoma in the ICH + NPAS4-siRNA group than in the ICH group (p < 0.05), which revealed that NAPS4 deficiency could reduce the infiltration degree of neutrophils." (PMID 37176030, 2023). "The principal component analysis indicated that many cytokines related to inflammation and activated immune system (myeloperoxidase, Il-6, Il-8 and MCP-1) as well as many angiogenic factors (angiopoetin-2, VEGF-A) were found to be significantly more expressed in hematoma." (PMID 32325892, 2020).
interstitial nephritis (6 papers, 2018 to 2025). Inflammation of the renal tubules and supporting tissues of the kidney. "We attributed interstitial nephritis with classical PTCitis in the setting of MPO-ANCA positivity to ANCA AAV." (PMID 39803122, 2024). "AAV-associated interstitial nephritis tended to occur in aged patients with nonspecific symptoms and positive MPO-ANCA." (PMID 35759125, 2022). "AAV-associated interstitial nephritis in aged patients with nonspecific symptoms is usually associated with MPO-ANCA." (PMID 35759125, 2022). "Absence of CD117 and myeloperoxidase-positive cells in the interstitium rules out the possibility of myelogenous cause of the reported interstitial nephritis." (PMID 32353102, 2020). "The most prominent localization of MPO, HNE and IL-8 in HFRS patients was the tubulointerstitial space, in line with the diagnosis of tubulointerstitial nephritis." (PMID 30283445, 2018).
intracranial aneurysm (6 papers, 2020 to 2024). "Previous reports demonstrated that MPO not only contributed to the formation and rupture of cerebral aneurysm but was also correlated with the degenerative remodeling predisposition to saccular intracranial aneurysm wall rupture, although its underlying mechanisms remain to be explored." (PMID 34611229, 2021). "Moreover, previous reports demonstrated that MPO not only contributed to the formation and rupture of cerebral aneurysm, but was also correlated with the degenerative remodeling predisposition to saccular intracranial aneurysm wall rupture." (PMID 34611229, 2021). "Elevated levels of the pro-inflammatory enzyme myeloperoxidase (MPO) are widely implicated in the pathogenesis of AAA, intracranial aneurysms, in other cardiovascular diseases, and in inflammation across multiple body systems." (PMID 33715602, 2021). "In patients with ruptured intracranial aneurysms, the expression of MPO was up-regulated with promoted expression of circRNA_0079586 and circRNA_RanGAP1." (PMID 34611229, 2021). "In another study, 36 saccular intracranial aneurysms from human cases, 16 unruptured and 20 ruptured lesions, were immuno-stained and positive signals for MPO were detected in all aneurysm lesions." (PMID 33203959, 2020).
liver cirrhosis (6 papers, 2005 to 2024). "Leukocytes also play a role in promoting liver cirrhosis by secreting myeloperoxidase (MPO), which can activate HSCs." (PMID 38275754, 2023). "This is the first evaluation of MPO-DNA and H3Cit-DNA in plasma from patients with liver cirrhosis and various degrees of liver dysfunction (Child–Pugh A to C), with or without concurrent HCC." (PMID 34504150, 2021). "The results suggested that several molecules were modulated, such as macrophage inflammatory protein 3α (MIP-3α)/chemokine ligand 20 (CCL20), nitric oxide (NO), thromboxane 2 (TXB2) and myeloperoxidase (MPO), indicating the therapeutic potential of probiotics on liver cirrhosis." (PMID 30297615, 2018). "We asked if plasma levels of the NET markers myeloperoxidase (MPO)-DNA and citrullinated histone H3 (H3Cit)-DNA, are elevated in liver cirrhosis and hepatocellular carcinoma (HCC) and if the levels correlate with clinical parameters." (PMID 34504150, 2021). "We therefore determined markers of NETs in plasma of patients with liver cirrhosis and HCC both with MPO-DNA, a standard method in use for several years, and the recently developed H3Cit-DNA assay." (PMID 34504150, 2021). "Similarly, an insignificantly higher median percentage of LDG fraction expressing MPO (1.4 vs. 0.5 [%]; p = 0.3425) in non-cirrhotic patients, as compared to the patients who have had cirrhosis of the liver was noted." (PMID 35456267, 2022).
Lymphadenopathy (6 papers, 2015 to 2025). Enlargement (swelling) of a lymph node. "In combination with morphology, MPO expression within histiocytes is an unusual finding in benign lymphadenopathies and has been reported as a characteristic immunophenotypic feature of Kikuchi's disease." (PMID 40682358, 2025). "On the other hands, less common findings including ground glass opacity, thickening of interlobular septa, lymphadenopathy, and pleural effusion, were more frequently observed in MPO-ANCA positive cases in the present study." (PMID 26223225, 2015). "All the other findings, such as ground glass opacity, thickening of interlobular septa, lymphadenopathy, and pleural effusion, were more frequently observed in MPO-ANCA positive cases (67 %, 33 %, 50 %, and 33 %, respectively)." (PMID 26223225, 2015).
myeloid leukemia (6 papers, 2012 to 2024). A clonal proliferation of myeloid cells and their precursors in the bone marrow, peripheral blood, and spleen. "The high expression of MPO from myeloid cells, along with the fact that halogenated DNA can cause gene mutation and epigenetic changes, may explain how benzene is involved in bone marrow disorders or myeloid leukemia." (PMID 21859636, 2012). "Due to the involvement of neutrophil-derived reactive oxygen species in many diseases and importance of NADPH oxidase and MPO-mediated reactions in progression and treatment of myeloid leukemia, monitoring this process and modulating it by pharmacological interventions is of great interest." (PMID 29416750, 2018). "The MPO protein was present in neutrophils located in amoebic hepatic lesions, which could be related to the findings of a previous study reporting that MPO is produced in the early stages of the development of myeloid leukemia and is stored in the cytoplasmic vesicles of neutrophils and monocytes." (PMID 28796788, 2017). "Because myeloid cells copiously express MPO and because halogenated DNA may induce both genetic and epigenetic changes that contribute to carcinogenesis, halogenative stress may account for benzene-induced bone marrow disorders and myeloid leukemia." (PMID 21859636, 2012). "The presence of myeloid specific markers, such as MPO, CD117, CD99 and CD34 should be helpful in making a diagnosis of myeloid leukemia first presenting in skin or cutaneous myeloid sarcoma." (PMID 23388086, 2013).
osteoporosis (6 papers, 2021 to 2026). A condition of reduced bone mass, with decreased cortical thickness and a decrease in the number and size of the trabeculae of cancellous bone (but normal chemical composition), resulting in increased fracture incidence. "This study identified PDPK1, MAP1LC3B, ZFP36, DRAM1, and MPO as potential biomarkers and proposes a nomogram based on hub genes for predicting osteoporosis risk." (PMID 39791175, 2025).
Peri-Implantitis (6 papers, 2020 to 2025). An inflammatory process with loss of supporting bone in the tissues surrounding functioning DENTAL IMPLANTS. "The results showed the peri-implantitis group had statistically significant higher MPO and ALP at baseline and 3 months post treatment compared to healthy sites (p < 0.001)." (PMID 36360962, 2022). "An analysis of grafted peri-implantitis connective tissues showed the expression of CD68, MPO and iNOS surface proteins." (PMID 37232785, 2023). "In peri-implantitis epithelial cells, membranous proteins expression showed differences in the levels of γ-H2AX, iNOS, NOX2, MPO and the PAD4/MPO ratio." (PMID 37232785, 2023). "Thus, in addition to aMMP-8, MMP-8 per TIMP-1, PMN elastase and MPO, seem to be possible alternatives for BOP as more accurate indicators of peri-implant tissue destruction and peri-implantitis." (PMID 32764436, 2020). "In this study, an aMMP-8 peri-implant sulcular fluid point-of-care-test diagnosed peri-implantitis and healthy implants far more accurately than bleeding-on-probing or the other biomarkers, such as polymorphonuclear (PMN)/neutrophil elastase, myeloperoxidase and MMP-9." (PMID 32764436, 2020).
Pleural effusion (6 papers, 2015 to 2025). The presence of an excessive amount of fluid in the pleural cavity. "Clinicians should consider MPA in patients with refractory interstitial pneumonia, pleural effusion, and myeloperoxidase ANCA positivity." (PMID 40988257, 2025). "It was observed that pleural effusion was more frequent in treatment-resistant patients, which might relate to MPO-ANCA activity." (PMID 37503353, 2023). "An additional study has reported that Sivelestat reduces the content of pleural effusion as well as levels of albumin (a marker of lung permeability), decreases myeloperoxidase activity (indicating neutrophil infiltration), amplifies oxygenation, and improves the survival rate." (PMID 34869231, 2021). "Interestingly, the level of MPO in children with pleural effusion was significantly higher than in children without pleural effusion." (PMID 26752656, 2016).
primary biliary cholangitis (6 papers, 2017 to 2025). Primary biliary cholangitis (PBC) is a chronic and slowly progressive cholestatic liver disease of autoimmune etiology characterized by injury of the intrahepatic bile ducts that may eventually lead to liver failure. "Studies on primary biliary cirrhosis have already demonstrated that infiltrating MPO+ or CD68+ inflammatory cells, mainly neutrophils or macrophages, participated in bile duct damage through nitric oxide and ROS." (PMID 28458256, 2017). "The aim of this study was to evaluate the frequency of ANCAs using indirect immunofluorescence (IIF) and the frequency of PR3-ANCA and MPO-ANCA specifically using ELISA for PSC/IBD+, PSC/IBD-, different types of AIH, and primary biliary cholangitis (PBC)." (PMID 33567045, 2021).
primary sclerosing cholangitis (6 papers, 2014 to 2025). "The term atypical pANCA (with perinuclear luminescence in method of indirect immunofluorescence) determines antibodies nonreactive towards myeloperoxidase, which can be detected mainly among patients with IBD and primary sclerosing cholangitis – PSC." (PMID 29991970, 2018).
rheumatic diseases (6 papers, 2012 to 2025). "Notably, SLE patients had the highest MPO levels compared with other rheumatic diseases, which is also evident in the estimated marginal means plot." (PMID 41465552, 2025). "Thus, MPO seems to be an effective mediator in the development of rheumatic diseases, presumably accompanied by necrosis of the cartilage cells." (PMID 39199167, 2024). "The possible evolution in a definite rheumatic disease and the unresolved questions about the treatment of these patients should be taken into account in a future revision of the IPAF criteria, evaluating the inclusion of anti-MPO antibodies." (PMID 34207641, 2021).
skin cancer (6 papers, 2014 to 2023). "Quercetin has shown activity against the myeloperoxidase (MPO) enzyme induced by UV-B radiation, contributing to preventing the development of skin cancer." (PMID 35694174, 2022). "GSPs inhibited UVB-induced infiltration of proinflammatory leukocytes and the levels of myeloperoxidase (MPO), Cox-2, PGE2, Cyclin D1, and PCNA in the skin and skin tumors compared to non-GSPs-treated UVB irradiated counterpart." (PMID 24757666, 2014).
ST Elevation Myocardial Infarction (6 papers, 2015 to 2025). A myocardial infarction that produces elevation in the ST segments of the ECG. "A significant positive correlation between oxLDL and MPO in plasma from patients with ST-elevation myocardial infarction has been reported." (PMID 31447863, 2019). "Indeed, chronically elevated plasma MPO levels found in human patients following ST-elevation myocardial infarction (STEMI) are a predictor of poor outcome." (PMID 31602405, 2019). "We studied the effects of stem cell treatment in ST-elevation myocardial infarction (STEMI) on PTX3 and MPO levels." (PMID 28197227, 2015).
urinary tract infection (6 papers, 2014 to 2025). "Regarding urinary tract infections, some proteins have been identified as potential biomarkers, such as lactoferrin (LF), xanthine oxidase (XO), and myeloperoxidase (MPO)." (PMID 37189669, 2023).
uveitis (6 papers, 2017 to 2025). An inflammatory process affecting a part of or the entire uvea. "The NAG and MPO levels were significantly higher in the uveitis group and in the DX group than in the naïve group." (PMID 36678822, 2023). "The primary oxidizing agent that interacts with luminol to generate the bioluminescence signal is believed to be hypochlorous acid generated by the activity of myeloperoxidase, but other oxidizing agents may be generated in these models of uveitis that contribute to the bioluminescence signal." (PMID 28278321, 2017). "Under the circumstances, serum IgG4 as well as MPO-ANCA and PR3-ANCA should be measured in patients with uveitis, especially APMPPE." (PMID 39493066, 2024). "This is of particular interest because the magenta module comprised mostly neutrophil enzymes, such as myeloperoxidase and elastase, and may reflect neutrophil functions that are relevant for the pathologic features of noninfectious uveitis." (PMID 36245752, 2022).
agranulocytosis (5 papers, 2011 to 2023). "This oxidation process is mediated by myeloperoxidase and cytochrome P450, which might explain why some drugs that induce granulocytopenia or agranulocytosis are hepatotoxic." (PMID 37077285, 2023). "A possible interaction of thyrostatic drugs with myeloperoxidase may therefore also lead to the formation of reactive metabolites in neutrophils and thus to the formation of modified proteins that act as antigens and contribute to the initiation of agranulocytosis." (PMID 34483939, 2021). "Myeloperoxidase and NADPH-oxidase are functionally involved in the pathogenesis of the drug-induced agranulocytosis." (PMID 21483481, 2011). "Even in patients who genetically had low myeloperoxidase activity, the tendency to develop clozapine-induced agranulocytosis was not reduced." (PMID 34483939, 2021).